HMGB1 (high mobility group box 1)
Diseases named in the same sentence as HMGB1 in open-access papers (continued):
Sharing a sentence is not in itself a finding about the gene and the disease.
cancer (continued). "We did not observe any association between circulating HMGB1 levels and muscle disease activity measures, antisynthetase antibodies or the presence of cancer." (PMID 32363191, 2020). "Due to its cellular functions, and link to key protein targets, we hypothesised that HMGB1 is important in the pathogenesis of BO to cancer." (PMID 31831860, 2020). "HMGB1 derived from dying cancer cells may bind to TLR4 on the APC and appears to contribute to the maturation of DCs, as well as to T cell responses and production of type I interferons." (PMID 30813267, 2019). "Furthermore, HMGB1 released from cancer cells necrotized by chemotherapy promotes regrowth of the remaining cancer cells and reduces anticancer drug responsiveness." (PMID 31905926, 2019). "In the context of cancer, HMGB1-mediated inflammation is certainly significant." (PMID 31379812, 2019). "The TLR2/HMGB1 axis promotes natural killer (NK) and cancer stem cell activation." (PMID 30306212, 2019). "Extracellular HMGB1 on cancer cell stemness has gathered increasing attention." (PMID 31558702, 2019). "Hence, it is assumed that HMGB1-mediated TLR4 signaling is involved in NET-induced cancer cell migration." (PMID 31034495, 2019). "This multi-activity of extracellular HMGB1 in the regulation of the cancer cell biology may depend on its secretory manner, redox status, cleavage, and special binding receptors." (PMID 31558702, 2019). "HMGB1 promotes cancer cell proliferation in human GBM U87MG and T98G cells." (PMID 31100066, 2019). "However, HMGB1 can a candidate chemotactic factor, because it is released from NETs and acts as a chemoattractant for cancer cells." (PMID 31034495, 2019). "Theoretically, a disappearance of possible cancer-induced proteolytic agents including HMGB1 could reduce muscle proteolysis." (PMID 31694176, 2019). "Moreover, HRE luciferase activity, indicated HIF-1α DNA binding ability, was enhanced in HMGB1 treated CD133− cancer cells and suppressed in the presence of EP under hypoxia." (PMID 31558702, 2019). "Moreover, the HMGB1 treated model has a higher percentage of CD133+ cancer cells, which were abrogated by HMGB1 antibody treatment." (PMID 31558702, 2019). "Although information available in the current literature can vary regarding the role, localization and clinical relevance of HMGB1, it is of extreme interest to explore its prognostic and biomarker potential, since it appears to be altered in so many human cancers." (PMID 31379812, 2019). "Furthermore, YAP knockdown significantly decreased HIF-1α expression and inhibited HMGB1/TLR2 induced CD133− cancer cell dedifferentiation." (PMID 31558702, 2019). "EP is reported to inhibit cancer cell growth and invasion by suppressing HMGB1-RAGE-NFκB axis." (PMID 31905926, 2019). "Interestingly, we found YAP phosphorylation(Ser397), which is associated with YAP protein degradation, was significantly reduced in CD133− cancer cells treated with HMGB1+ irradiated cells or rhHMGB1." (PMID 31558702, 2019). "These researches indirectly confirmed the role of HMGB1 in cancer cells plasticity." (PMID 31558702, 2019). "In addition, CAF-derived HMGB1 promotes TERT expression in cancer cells and induces stem cell properties." (PMID 31905926, 2019). "HMGB1 have previously shown to play important roles in inflammation and cancer." (PMID 30292233, 2018). "According to our results, radiation-based combination therapy with a molecular HMGB1 inhibitor could serve as a potential option for cancer treatment." (PMID 29844348, 2018). "HMGB1, a cytokine, has extracellular functions in inflammation and cancer progression." (PMID 29568761, 2018). "We next tested whether the in vitro observation of dying cell-released HMGB1 promoting cancer cell invasion could be replicated in vivo." (PMID 29615080, 2018). "HMGB1 has been reported to be involved in diseases such as arthritis, sepsis, and cancer." (PMID 29463261, 2018).
cancer (continued). "Although the exact molecular function of HMGB1 in cancer is largely unknown, early studies describe circulating HMGB1 as a useful tool and biomarker for malignant tissue or monitoring therapy." (PMID 30123419, 2018). "Increased HuR promoted cancer cell proliferation and the metastasis potential partly by HMGB1." (PMID 29728635, 2018). "Additionally, HMGB1 promotes expression of anti-apoptotic Bcl-2 family members and calnexin and inhibits pro-apoptotic cIAP expression, thus protecting cancer cells from apoptosis." (PMID 30157958, 2018). "Furthermore, inflammatory factor expression decreased for neutrophils that were treated with exosomes from HMGB1-silenced cancer cells compared to exosomes from cells transfected with scramble control siRNA." (PMID 30292233, 2018). "Transcription regulation necessitates the presence of HMGB1 in many cancer genes." (PMID 30245980, 2018). "Further, HMGB1 is involved in cancer progression and observed in various types of cancers." (PMID 29568761, 2018). "In addition, HMGB1 is frequently highly expressed in various malignant tumors and is an early marker for these tumors." (PMID 29850505, 2018). "Taken together, these results demonstrated that HMGB1 released from dying cancer cells after neoCRT may enhance regrowth and metastasis of remnant cancer cells via RAGE-ERK-Drp1 activation." (PMID 30258050, 2018). "In addition, during anticancer therapy, redox states of HMGB1 are also able to regulate the fate of a cancer cell toward cell death or cell survival." (PMID 29636841, 2018). "Therefore, high HMGB1 expression can be used as a potential clinical marker, linking to aggressiveness and disease progression in patients with cancer." (PMID 29844348, 2018). "As a common DAMP, the HMGB1-expression level is elevated in certain cancer types." (PMID 29615080, 2018). "Multiple reports indicate that recombinant HMGB1 is directly cytotoxic to some cancer cell lines." (PMID 29543735, 2018). "HMGB1 has been reported to be involved in cancer development, invasion, and metastases." (PMID 29850505, 2018). "The results showed that HMGB1 is localized adjacent to cleaved Caspase-3 positive cancer cells." (PMID 29615080, 2018). "Recently, neutrophil extracellular traps (NETs), whereby activated neutrophils release their intracellular contents containing DNA, histones, tissue factor, high mobility group box 1 (HMGB1) and other components have been implicated in PDA and in cancer-associated thrombosis." (PMID 29929491, 2018). "Moreover, we noticed that the number of migrating cancer cells in the N-S + EP-treated group was much less than in the HMGB1−/−-S-treated group, indicating EP as an additional mechanism in inhibiting cell invasion." (PMID 29615080, 2018). "Finally, we showed that dying-cell-derived HMGB1 functions in a paracrine manner to affect cancer-cell migration dependent on acquiring an epithelial-mesenchymal transition (EMT) phenotype and PI3K/pAkt activation." (PMID 29615080, 2018). "Current knowledge is that HMGB1 may play paradoxical roles in cancer, although its exact mechanism and physiological meaning still remain to be further investigated." (PMID 30049847, 2018). "In addition, HMGB1 mediates the transcription regulation of E-selectin, TNF-α, BRCA1, and insulin receptor in association with cancer genes." (PMID 29636841, 2018). "HMGB1 has been shown to promote cancer cells’ proliferation." (PMID 29615080, 2018). "HMGB1 release from fibroblast and other host and cancer cells might serve as a way to limit virus replication during lytic infection." (PMID 29543735, 2018). "HMGB1 has been shown to induce epithelial-mesenchymal transition (EMT) in cancer cells." (PMID 29636841, 2018). "HMGB1 is widely convinced as one of the most cancer-specific genes." (PMID 30049847, 2018).
cancer (continued). "Besides directly damaging cardiomyocytes, doxorubicin induces apoptosis of immune (e.g., macrophages) and cancer cells releasing high mobility group box 1 (HMGB1) which, in turn, triggers toll-like receptor (TLR)-2 and-4." (PMID 29563880, 2018). "However, cancer cells exposed to N-S and rhHMGB1 showed significantly more and larger metastatic foci than HMGB1-/--S and N-S + EP groups." (PMID 29615080, 2018). "Moreover, the inhibition of mitochondria fission via Drp1, the blockage of the release of HMGB1 or the blockage of the HMGB1 receptor RAGE enhance the sensitivity of anti-cancer agents in CRC." (PMID 30258050, 2018). "Dendritic cells are also activated by HMGB-1, which is produced by necrotic cancer cells (NCs)." (PMID 29420595, 2018). "Studies also demonstrated that HMGB1 plays an important role in cancer metastasis." (PMID 29728635, 2018). "HMGB1 and HMGB2 are members of the High Mobility Group (HMG) protein superfamily that contain a DNA binding domain (HMG-Box), and their overexpression has been associated to main cancer hallmarks, tumor progression, metastasis formation and bad prognosis." (PMID 29721183, 2018). "Our results suggest that inhibition of HMGB1 could contribute to the protective effect of metformin against cardiovascular diseases and cancer in diabetic patients." (PMID 28373282, 2017). "Moreover, evidences confirm that HMGB1 over-expression is closely related to tumour development through functions in proliferation, invasion and migration of cancer cells." (PMID 28423715, 2017). "Our results characterised HMGB1 as a potential target of miR-200c and showed that miR-200c may regulate A549 cell EMT, and cancer progression by targeting HMGB1." (PMID 28727734, 2017). "Our results indicate that CBP501 suppresses the ABCG2 expression on cancer cell surfaces that may be induced in a co-culture system upon stimulation with LPS or HMGB1." (PMID 28969049, 2017). "Activation of HMGB1 can induce autophagy in cancer and immune cells." (PMID 28642840, 2017). "Furthermore, many studies have demonstrated that HMGB1 can promote malignant phenotypes of cancer cells through increasing proliferation, EMT, and metastasis." (PMID 28727734, 2017). "HMGB1 is also related to the chemoresistance and radioresistance in various cancers." (PMID 28376901, 2017). "Additionally, Carbenoxolone was found to be an antagonist of the cytokine activity of RAGE ligand, HMGB1 protein, a potent mediator of two cancer promoting processes; angiogenesis and inflammation." (PMID 28415753, 2017). "Crosstalk between HMGB1 and apoptosis has been explored in many cancer cells." (PMID 28969092, 2017). "Furthermore, we would like to present current strategies targeting against HMGB1, its receptor or release, which have shown potentially therapeutic value in cancer intervention." (PMID 28969092, 2017). "Neutralizing antibodies to IL-6 or histone H3 or knockout of the receptor for advanced glycation end products all limit K-Ras signaling activation, prevent cancer development and metastasis/invasion, and prolong animal survival in Pdx1-Cre;K-RasG12D/+;Hmgb1−/− mice." (PMID 28374746, 2017). "Of recent interest is the role of HMGB1 as a positive regulator of autophagy in cancer." (PMID 29254158, 2017). "HMGB1 can be passively released by necrotic cells and also actively secreted by inflammatory cells and by some cancer cells into the extracellular milieu, where it acts as a damage-associated molecular pattern (DAMP) and mediates inflammation or plays a role as chemo-attractant factor." (PMID 28186988, 2017). "Interestingly, some of the cancer-promoting effects of HMGB1 appear to be mediated through alterations in cancer cell mitochondrial bioenergetics." (PMID 28531105, 2017). "Our present data suggest that plasma HMGB1 may be a predictive and/or prognostic marker for cancer vaccine therapy, although at the present time, there remains no direct correlation with OS." (PMID 28536706, 2017).
cancer (continued). "Besides, HMGB1 is passively released from cancer cells or actively secreted by inflammatory cells in response to anticancer treatment." (PMID 29069735, 2017). "HMGB1 accelerates the formation of filopodia and there by regulates cancer metastasis." (PMID 28727734, 2017). "HMGB1 release is involved in the immune response against cancer cells." (PMID 28771183, 2017). "HMGB1 is expressed in all mammalian cells and is overexpressed in various types of cancer cells." (PMID 28415753, 2017). "Furthermore HMGB1-dependent activation of TLR9 pathways was found to occur in cancer cells upon exposure to NETs and to increase proliferation, invasion and migration." (PMID 28166238, 2017). "HPLC isolation of HMGB1 from Nkp30-stimulated supernatants and subsequent transfer to IgG1 control supernatant resulted in substantial cytotoxicity and confirmed that HMGB1 is an important factor that has the specific ability to kill cancer cells." (PMID 26948869, 2016). "In vivo, HMGB1 promoted lymphangiogenesis in the pathological process of cancer." (PMID 27100831, 2016). "In this study, we have hypothesised that HMGB1 is released from cancer cells under tumour microenvironmental stress conditions and that this protein promotes proliferation, migration and invasion of myofibroblasts." (PMID 26979829, 2016). "Taken together, both enhanced glucose fermentation and increased glutaminolysis might render cancer cells resistant to HMGB1 and animal experiments suggest that treatment with recombinant HMGB1 could represent a therapeutic option." (PMID 26948869, 2016). "In addition to these reports, recent evidence demonstrates that HMGB1 plays an important role in the tumorigenesis and progression of many types of cancers such as digestive system, urogenital system, skin, bone, and blood cancer." (PMID 27391431, 2016). "Our data suggest that HMGB1 released from cancer cells under glucose deprivation is involved in stimulating colonic myofibroblast migration and invasion and that this occurs through the activation of RAGE and TLR4, resulting in the activation of the MAPK and PI3K signalling pathways." (PMID 26979829, 2016). "The exact mechanisms by which HMGB1 regulates Wnt signalling and intestinal stem cells remains to be determined, however, our work adds to the accumulating evidence implicating HMGB1 has potential for cancer therapy." (PMID 27323825, 2016). "HMGB1 is also related to the hallmarks of cancer as described by Hanahan and Weinberg." (PMID 26682011, 2016). "However, our work provides evidence that Hmgb1 is a potential Wnt signalling target gene and contributes to the body of evidence implicating Hmgb1 in cancer formation with the potential for exploitation as a therapeutic target." (PMID 27323825, 2016). "Because of the strong inhibition of aerobic respiration by HMGB1 in cancer cells with relatively high mitochondrial respiration (SW480, HCT116), we hypothesized that cancer cells adapted to anaerobic metabolism could be resistant to HMGB1." (PMID 26948869, 2016). "In addition, this study provides a novel insight into the therapeutic strategy targeting HMGB1 by PPAR ligands for human cancer, more than only for inflammatory disorders." (PMID 27563308, 2016). "Consequently, NK cell-mediated cell death induced via HMGB1 particularly targets cancer cells that rely on oxygen-dependent energy metabolism." (PMID 27652323, 2016). "Cancer cells infected by an oncolytic poxvirus undergo programmed necrosis and apoptosis with release of ATP, HMGB1 as well as immunogenic endoplasmic reticulum chaperone gp96, all danger signals to the innate immune system, making it a type of immunogenic cell death (ICD)." (PMID 26956047, 2016). "For example doxorubicin induces the secretion of a protein called high-mobility-group box 1 (HMGB1) from dying cancer cells that binds to toll-like receptor (TLR) 4 on dendritic cells resulting in the secretion of IFN-g, antigen presentation, and activation of T-cells." (PMID 27777769, 2016).
cancer (continued). "Besides this acetylation, phosphorylation and methylation of HMGB1 are also shown to be related to its translocation during the secretion process in inflammatory or cancer cells." (PMID 27563308, 2016). "Extracellular HMGB1 can play further roles in cancer through the activation of endothelial cells." (PMID 27294158, 2016). "HMGB1 inhibitors or RAGE suppressants may be effective in prohibiting cancer regrowth, supported by HMGB1-related autophagy during chemotherapy." (PMID 25652880, 2015). "Here, we examined whether carbon-ion beams, as well as X-rays, can induce HMGB1 release from human cancer cell lines." (PMID 25755254, 2015). "However, it was observed that ability of mice to resist rechallenge was comprised when the mice were immunized with HMGB1-depleted CT26 cancer cells or by co-injection of HMGB1-specific antibody." (PMID 26625309, 2015). "Therefore, the role of HMGB1 in cancer development and progression, as well as its effect on the response to treatment, remains largely unexplored." (PMID 25622595, 2015). "HMGB1 is a chaperone, which has been reported to be present in all nucleated cells and to be expressed in normal and pathological conditions, including inflammation, cancer, and autoimmune disorders." (PMID 25385222, 2015). "However, HMGB1 again plays a dual role as it was also shown to induce apoptosis in macrophage-derived dendritic cells, weakening the body’s anti-cancer immune response." (PMID 26854151, 2015). "HMGB1 as DAMPs has been widely demonstrated in necrotic cancer cells." (PMID 26625309, 2015). "As a crucial mediator in pathological angiogenesis, VEGF-A is largely responsible for vascularization in malignant tumours 23, and HMGB1 has been implicated in VEGF-A production in several non-malignant circumstances 24–27." (PMID 26099505, 2015). "Moreover, HMGB1 has been demonstrated as a critical role in a number of cancers, including colorectal, breast, lung, prostate, cervical, skin, kidney, gastric, pancreatic, osteosarcoma and leukemia." (PMID 26393575, 2015). "However, the functions of HMGB1 in cancer are complicated and paradoxical because of its difference of intracellular and extracellular locations." (PMID 26393575, 2015). "Most cancer therapies, such as radiation and anti-cancer drugs, induce cancer cells to undergo autophagy, which is an important mechanism of resistance to therapy; thus, mechanisms involving HMGB1 might be key regulators of resistance to anti-cancer therapies." (PMID 25622595, 2015). "Moreover, extracellularly-reduced HMGB1 promotes autophagy in a RAGE-dependent manner, whereas oxidized HMGB1 triggers caspase-dependent apoptosis in cancer cells." (PMID 25904867, 2015). "Thus, we propose HMGB1 release as a pro-survival signal for residual cells following various cytotoxic cancer treatments." (PMID 25652880, 2015). "RAGE activation via its multiple ligands, including HMGB1, plays a key role in various diseases, including acute or chronic inflammatory conditions such as sepsis and diseases such as rheumatoid arthritis, diabetic nephropathy, and cancer." (PMID 25385222, 2015). "In contrast, in the low differentiated cancer cells, HMGB1 normally resided in the nucleus." (PMID 26393575, 2015). "However, recent studies suggest that HMGB1 can be released in apoptosis by macrophages, cancer cells, and other cells." (PMID 25904867, 2015). "Therefore, carbon-ion beams are as effective as X-rays at inducing HMGB1 release from different types of human cancer cells." (PMID 25755254, 2015). "For moderately differentiated cancer cells, the localization of HMGB1 was perinuclear." (PMID 26393575, 2015).